NLRP3 (NLR family pyrin domain containing 3)
Diseases named in the same sentence as NLRP3 in open-access papers (continued):
Sharing a sentence is not in itself a finding about the gene and the disease.
tumor (continued). "Moreover, we focus on the therapeutic potential of targeting NLRP3 for cancer therapy, emphasizing how understanding NLRP3 inflammasome-dependent cancer mechanisms might guide the development of new drugs that target the inflammatory response of tumor-associated cells." (PMID 34064909, 2021). "A preclinical study found that pharmacologic inhibition of NLRP3 suppressed G-MDSC tumor infiltration and significantly enhanced anti-PD-1 efficacy." (PMID 33258011, 2021). "Rather, our studies implicate HSP70 as being the critical soluble mediator released by the tumor NLRP3 inflammasome as well as the driver of PMN-MDSC recruitment in several murine models and human tumor cell lines." (PMID 34638239, 2021). "We demonstrate that tumor-derived NLRP3 activation induces MDSC expansion, which suppresses recruitment and activation of antitumor immunity." (PMID 33649199, 2021). "Remarkably, we observed increased nuclear NLRP3 expression in tumor lesions and during disease progression, which was also strongly correlated with IL-4 expression." (PMID 34220814, 2021). "Considering the heterogeneity of tumor cells, the expression of NLRP3 inflammasome in the P+ tumor tissues was mainly activated." (PMID 34660289, 2021). "The downregulation of NLRP3 in CLL lymphocytes blocks cell proliferation and induces apoptosis, suggesting that the NLRP3 inflammasome works as a negative regulator of tumor growth." (PMID 34064909, 2021). "Depending on the type of cancer, NLRP3 can have opposing functions, either promoting tumor formation or, as some studies show, counteracting tumor development." (PMID 33525345, 2021). "Inhibition of tumor-derived NLRP3 results in reduced PMN-MDSCs expansion from the bone marrow and less infiltrating MDSCs in the TME." (PMID 34531850, 2021). "Overall, these data indicate that tumor-derived NLRP3 activation induces local host inflammatory cytokines, which fuel systemic inflammation." (PMID 33649199, 2021). "Here, we summarize the impact of NLRP3 and inflammatory Gzm in developing inflammatory diseases and the anti-tumor efficacy of immune cells." (PMID 34685542, 2021). "Our data showing tumor-intrinsic NLRP3 to drive HSP70 release further suggests the use of plasma HSP70 levels as another candidate predictive biomarker for either NLRP3 or HSP70-targeted inhibitors." (PMID 34638239, 2021). "To further study the mechanism of HDSB11 in inhibition of cell proliferation and tumor growth, we tested the expression of NLRP3 in tumor tissues and cells." (PMID 34239588, 2021). "The P2RX7 receptor is responsible for making NLRP3 sensitive to ATP, which is one of the main DAMPs released during inflammation and is highly expressed in tumor cells." (PMID 33972620, 2021). "To this end, we first investigated the effect of DPP-4i on NLRP3 activation, a critical inflammasome in the remodeling of tumor microenvironment." (PMID 34631556, 2021). "As shown in the boxplot, IL1B, MST1, GBP1, and NLRP3 were downregulated, and the other 35 PRGs were upregulated in tumor tissues." (PMID 34869364, 2021). "Our findings suggest that doxycycline inhibits LPS priming of NLRP3 and reduces tumor progression through early apoptosis in cancer." (PMID 34577552, 2021). "Recently, it has been proposed that CAFs sense DAMPs and thus activate the NLRP3 inflammasome pathway, leading to proinflammatory signaling and IL-1β release, which promote tumor progression and lung metastasis." (PMID 34064909, 2021). "Thus, although the NLRP3 inflammasome plays an important role in various immune cells, including macrophages, it also might be expressed in human cancers and be implicated in tumor development and metastasis." (PMID 34502191, 2021). "In this study, we found that overexpressed NLRP3 and DNA damage were simultaneously found in the tumor tissues of P+ group, promoting tumor growth and proliferation." (PMID 34660289, 2021).
tumor (continued). "NLRP3 has been known for a long time and can be involved in many physiological and pathological processes, including tumor progression." (PMID 34930938, 2021). "Together, these data outline a role for the tumor-intrinsic NLRP3 inflammasome in driving acquired resistance to checkpoint inhibitor immunotherapy by triggering the recruitment of an immunosuppressive population of PMN-MDSCs." (PMID 34638239, 2021). "Here, we also demonstrated that propolis decreased the levels of proinflammatory mediators, including TNF-α, IL-1β, and IL-6, as well as NLRP3 inflammasome to improve the tumor inflammatory microenvironment." (PMID 33628847, 2021). "In the HNSCC murine model, a novel NLRP3 inhibitor MCC950 delayed tumor growth, reduced MDSCs, Tregs and TAMs, while also increasing T cell infiltration within the TME." (PMID 33572196, 2021). "The inhibition of the NLRP3 inflammasome pathway was suggested to be a promising approach for decreasing tumor cell invasion and survival." (PMID 34660289, 2021). "In this study we focused on NLRP3 inflammasome activation in the tumor counterparts to examine the activity of this complex in BC, evaluate its possible contribution to prognosis and provide indications for future combination therapies." (PMID 34540671, 2021). "A crucial study found that NLRP3 expression was upregulated in human CRC tissues compared to adjacent normal tissues and was associated with tumor invasion and poor prognosis." (PMID 34064909, 2021). "Upon knock-down of NLRP3 in the tumor, IL-1β processing is arrested and, therefore mature IL-1β-induced IL-6/STAT3 axis is no longer being amplified." (PMID 34531850, 2021). "Tumour promoting effect of the NLRP3 inflammasome can be reversed by downregulating its expression levels or pharmacological inhibiting their activity." (PMID 33918087, 2021). "As NLRP3 inflammasome activation usually leads to the autocleavage of caspase-1 and has pro-tumor growth effect in OSCC cells, we further detected the expression of NLRP3." (PMID 35004674, 2021). "Considering the observation that tumor-derived NLRP3 drives tumor progression, we measured the concentration of OLT1177 in the tumors." (PMID 33649199, 2021). "It has been shown that NLRP3 inflammasome activation in the tumor microenvironment has a critical role in the response to some chemotherapeutic agents." (PMID 33628847, 2021). "It was demonstrated that ATP released from dying tumor cells as a result of chemotherapy can act on P2X7 purinergic receptors (P2RX7) (most potent activator of the NLRP3 inflammasome) and trigger the activation of the inflammasome." (PMID 33840390, 2021). "While much of our understanding of NLRP3 biology has been derived from studies in myeloid cell populations, such as macrophages and dendritic cells, its tumor-intrinsic role has historically been overlooked." (PMID 34638239, 2021). "In contrast, in lung cancer, prostate cancer, breast cancer, and head and neck squamous cell carcinoma, the NLRP3 inflammasome, IL-1β, and IL-18 promote tumor growth, proliferation, invasion, and metastasis." (PMID 33534121, 2021). "Of note, NLRP3 also increased the expression of c-Myc and P21, which are important tumor-promoting genes to promote tumor progression." (PMID 34955826, 2021). "While the regulation of the NLRP3 inflammasome has been well examined within various myeloid populations of the innate immune system, very few studies have investigated the tumor-intrinsic properties of NLRP3." (PMID 34638239, 2021). "We also observed that with specific inhibition of NLRP3, both tumor volume and STAT3 signaling in the TME are significantly reduced." (PMID 34531850, 2021). "The associations of NLRP3 expression level with Age, Serum PSA, Gleason score, tumor size, TNM stage, and Lymph node migration of PCa patients were further explored in this study." (PMID 34930938, 2021).
tumor (continued). "In conclusion, alterations in NLRP3 inflammasome activation influence malignant transformation, tumor progression, and response to therapy by affecting an intricate network of cancer cell functions." (PMID 34064909, 2021). "Some studies have reported a tumor-suppressor function of NLRP3 inflammasome activation through an increase in pyroptotic cell death." (PMID 35008212, 2021). "The tumor-intrinsic NLRP3 inflammasome is a newly recognized player in the regulation of tumor-directed immune responses and promises to provide fresh insight into how tumors respond to immunotherapy." (PMID 34638239, 2021). "PTEN is an important tumour suppressor while NLRP3 also contributes to the response of cancer cells to some chemotherapeutic agents." (PMID 34854899, 2021). "Nevertheless, our understanding of the influence of genetic variation in NLRP3 on tumor behavior and tumor immunosurveillance remains poor." (PMID 34638239, 2021). "Pharmacological inhibition of NLRP3 in platelets resulted in decreased platelet activation and improved survival of tumor-bearing mice." (PMID 34976805, 2021). "Intriguingly, overexpression of the NLRP3 inflammasome in EBV-associated NPC was shown to associate with favourable clinical outcome, suggesting the role of the inflammasome in tumour suppression." (PMID 33918087, 2021). "While implicated in driving certain intrinsic tumorigenic properties of cancers, an important role for the NLRP3 inflammasome in directing anti-tumor immunity is now being realized." (PMID 34638239, 2021). "NOD-like receptor protein 3 (NLRP3)-inflammasome activation, interleukin-1β (IL-1β) secretion, and cancer cell-released extracellular vesicles (EVs) contribute to the establishment of tumor microenvironment." (PMID 34070682, 2021). "Accordingly, transcription factor EB (TFEB) modulates tumor-associated macrophage (TAM) gene expression in BC through several pathways, for example, by promoting NLRP3 inflammasome degradation." (PMID 34064909, 2021). "The immunotherapeutic blockade of PD-1 activated the NLRP3 inflammasome, which in turn led to the recruitment of granulocytic myeloid-derived suppressor cells into the tumor bed." (PMID 33806053, 2021). "The results of the tumor formation in nude mice showed that silencing of NLRP3 significantly slowed down the tumor growth of PCa." (PMID 34930938, 2021). "The data support the concept that tumor NLRP3 activation represents an intrinsic pathway that favors tumor immune escape." (PMID 33649199, 2021). "Activation of the NLRP3 inflammasome induces abnormal secretion of soluble cytokines, generating advantageous inflammatory surroundings that support tumor growth." (PMID 34540671, 2021). "The tumor-intrinsic NOD-like receptor family, pyrin-domain-containing-3 (NLRP3) inflammasome, plays an important role in regulating immunosuppressive myeloid cell populations in the tumor microenvironment (TME)." (PMID 34638239, 2021). "The NLRP3 inflammasome is an innate immune mediator responsible for active interleukin (IL)-1β biosynthesis and secretion, which is critical for tumor development and immunity." (PMID 34357109, 2021). "Inhibition of NLRP3 can inactivate caspase-1 and inhibit tumor cell proliferation and migration in many kinds of cancers." (PMID 34239588, 2021). "As the main effectors of NLRP3 inflammasome, IL-1β and IL-18 belong to the IL-1 superfamily and have the potential to promote an immune-suppressive tumor microenvironment." (PMID 34211462, 2021). "Aberrant NLRP3 inflammasome activation induces the overproduction of pro-inflammatory cytokines to form an inflammatory microenvironment and promotes tumour progression by reducing the drug sensitivity of tumour cells." (PMID 33918087, 2021). "Although several studies have reported the importance of the NLRP3 inflammasome as a regulator for tumor control, its role in human cancers remains controversial." (PMID 35008212, 2021).
tumor (continued). "NLRP3 inflammasome has also been found related to tumor pathogenesis, but its role in cancer is versatile and sometimes controversial." (PMID 34211462, 2021). "Increased expression of NLRP3 enhanced the induction and expansion of myeloid-derived suppressor cells (MDSCs) to the tumor microenvironments and resulted in suppression of antitumoral effects of T cells." (PMID 33821998, 2021). "This controversial role of NLRP3 in the tumor development of various cancer types was well-summarized by Hamarsheh and Zeiser." (PMID 33525345, 2021). "The NLRP3/Caspaseaspase-1/GSDMD pathway has been reported to be crucial for NLRP3 induced tumor progression." (PMID 34393801, 2021). "Similar results were obtained on inhibition of NLRP3 inflammasome-dependent neutrophil infiltration of these malignant lesions, indicating that excessively aging neutrophils support tumor growth." (PMID 34876407, 2021). "In colorectal liver metastases, the activation of NLRP3 inflammasome in KCs triggers IL-18 production, stimulating the maturation of NK cells and priming the FasL-mediated apoptosis of tumor cells." (PMID 35008212, 2021). "Additional studies have shown NLRP3 expression by MDSCs to mitigate against the anti-tumor properties of 5-fluorouracil chemotherapy in several preclinical tumor models by driving TH17 development." (PMID 34638239, 2021). "Here, we report how tumor-NLRP3 activity promotes IL-6/STAT3 signaling in the bone marrow, which then regulates immunosuppressive gene expression in PMN-MDSCs resulting in a defunct cell population." (PMID 34531850, 2021). "Taken together, these data suggest that a unified mechanism for NLRP3 inflammasome activation and its involvement in cancer has not yet emerged, so future studies are needed to better clarify its role in each kind of tumor." (PMID 34064909, 2021). "Overall, these data show that inhibiting tumor-NLRP3 alone is sufficient to reduce IL-6/STAT3 activation, resulting in the reduction of immunosuppressive gene expression in PMN-MDSCs." (PMID 34531850, 2021). "For example, NLRP3 inflammasome activation in tumor cells supports a chronic inflammatory microenvironment, which promotes malignant transformation and suppress local immunity." (PMID 34070682, 2021). "Experimental data demonstrated that natural products affected tumor growth and metastasis, partly regulating NLRP3 and relevant inflammatory signaling pathways." (PMID 34239588, 2021). "For example, the NLRP3 inflammasome enhances dendritic cell-mediated activation of T lymphocytes against tumor cells." (PMID 34502191, 2021). "IL-1β neutralization promotes intratumoral CD8+ T cell infiltration and function and sensitizes PDA to immunotherapy, confirming that the effects of tumor cell-derived IL-1β are NLRP3-dependent and identifying a tumor-supportive role for NLRP3 in PC." (PMID 34064909, 2021). "Upon the inhibition of NLRP3 inflammasome activation the tumor infiltration of the suppressive immune cells was reversed and the efficacy of anti-PD-1 immunotherapy was augmented." (PMID 33806053, 2021). "Ursolic acid is a natural compound that can up-regulate NLRP3 in RCC, then activate caspase-1, and eventually cause pyroptosis and inhibit tumor growth." (PMID 34869390, 2021). "Taken together, these data suggest tumor-NLRP3 as a potential target to suppress MDSCs, which ultimately dampen cytotoxic T cell functions." (PMID 34531850, 2021). "NLRP3 was notably downregulated in HCC tumor tissues and cell lines compared with normal tissues and LO2 cells." (PMID 34546972, 2021). "Overall, these findings support the concept that the NLRP3 inhibition added to anti–PD-1 has greater efficacy in reducing tumor growth compared to either agent as a monotherapy." (PMID 33649199, 2021). "In pancreatic cancer, ATP-induced NLRP3 inflammasome activation accelerates IL-1β production that subsequently increases tumour cell proliferation." (PMID 33918087, 2021).
tumor (continued). "The genetic and pharmacologic inhibition of NLRP3 suppressed PMN-MDSCs tumor infiltration and significantly augmented the efficacy of anti-PD-1 antibody immunotherapy in melanoma." (PMID 35003065, 2021). "By performing a pancancer analysis of NLRP3 inflammasome-related genes across 24 human cancers, Ju M. and colleagues found that 15 cancers had significant differences in NLRP3 expression between normal and tumor samples." (PMID 34064909, 2021). "Nevertheless, upon knockdown of tumor-derived NLRP3, tumor progression markedly slowed with anti-PD-1, resulting in decreased PMN-MDSC infiltration into the TME." (PMID 34531850, 2021). "Previously, we demonstrated that tumor cells release various amounts of IL-1β based on their ability to activate NLRP3." (PMID 34577552, 2021). "In tumor cell lines where NLRP3 activation and, IL-1β and IL-18 secretion are low, Nigericin demonstrated an anti-tumor effect." (PMID 33613529, 2020). "Following chemotherapy, the NLRP3 inflammasome plays an important role in priming tumor specific CD8+ T cells leading to an anti-tumor adaptive immune response." (PMID 33036374, 2020). "Meanwhile, the high expression level of NLRP3 inflammasome suggested poor prognosis in 121 LSCC tumor tissues." (PMID 32577124, 2020). "The role of the NLRP3 inflammasome is crucial for the immune response against dying tumor cells as it interacts with the adaptor molecule apoptosis-associated speck-like protein to induce caspase-1 activation." (PMID 33304353, 2020). "Tumor tissue sections in the HRW groups presented moderate-to-strong positive expression of NLRP3, caspase-1 and GSDMD." (PMID 31924176, 2020). "The NLRP3 inflammasome was considered as a positive regulator of tumor cell proliferation and metastasis." (PMID 32974137, 2020). "The inhibition of NLRP3 was seen to decrease MDSC tumor infiltration thereby increasing the efficacy of anti-PD-1 antibody immunotherapy." (PMID 33014808, 2020). "The anti-tumor activity of several compounds targeting NLRP3 inflammasomes was studied, including Nigericin and VX-765." (PMID 33613529, 2020). "When NLRP3 was activated, it appears that LPS and Nigericin upregulated different cytokines in tumor cells." (PMID 33613529, 2020). "Following tumor excision, IHC analysis was used to determine tumoral expression of apoptosis- and pyroptosis-related biomarkers, including NLRP3, IL-18, IL-1β, and caspase-1." (PMID 32209729, 2020). "The aryl hydrocarbon receptor (AHR), a potential tumor suppressor and NLRP3 regulator, was higher in hen (2.4x increase, p = 0.002) and human tumors (1.8x increase, p = 0.038), suggesting a role in OvCa." (PMID 31923221, 2020). "Tumor tissue sections in the HRW group presented much higher NLRP3, caspase-1 and GSDMD staining by IHC." (PMID 31924176, 2020). "Among all types of inflammasomes, NLRP3 has caught the attention of many research groups and presented tremendous interest due to its involvement in various types of tumor development." (PMID 33015196, 2020). "In the context of chemotherapy, a study provided evidence that the NLRP3 inflammasome including caspase-1 are important for the induction of tumor-specific IFNγ producing helper CD4+ T cells, since Th1 priming failed in NLRP3 or caspase-1 deficient mice." (PMID 32674488, 2020). "This allows the activation of the NLRP3 inflammasome, the production of IL-1β, leading to tumor progression and lung metastasis." (PMID 32635472, 2020). "In this study, we demonstrated that interaction between LC cells and macrophages by exosomal TRIM59 results in dysregulated NLRP3 inflammasome activity that drive macrophages-mediated tumor progression." (PMID 32867817, 2020). "Dying tumor cells release ATP, which activates the NLRP3 inflammasome in DCs allowing for the secretion of IL‐1β, a cytokine which is required for the polarization of IFN‐γ‐producing CD8+ T cells." (PMID 33179413, 2020).